INS (insulin)
Diseases named in the same sentence as INS in open-access papers (continued):
Sharing a sentence is not in itself a finding about the gene and the disease.
Obesity (continued). "It has been reported in previous studies that in lean individuals, blood flow accelerates after a glucose load, but in obesity and/or insulin-resistant subjects unaltered or lower ATBF and blunted postprandial responses have been observed." (PMID 28346464, 2017). "In contrast, recombinant osteocalcin administration improved insulin secretion and sensitivity and prevented high-fat-induced obesity and diabetes." (PMID 28194185, 2017). "Upregulation of UCP1 by genetic manipulations or pharmacological agents can reduce obesity and improve insulin sensitivity." (PMID 28360931, 2017). "It became clear that low-grade inflammation is a key feature of obesity and T2D by the fact that the excess of pro-inflammatory cytokines impairs cellular insulin signalling." (PMID 29101397, 2017). "The metabolic profile of the insulin-sensitive men with obesity in the present study was consistent with previous reports, including lower glycaemia, fasting insulin, and CRP." (PMID 28293196, 2017). "C57Bl/6 mice fed a HFD develop massive obesity related pathologies including fat deposition in various organs, altered plasma lipids and impaired insulin sensitivity." (PMID 29088722, 2017). "Autophagy has important protective metabolic functions, including maintenance of insulin sensitivity and degradation of intracellular lipids, under metabolic conditions, such as obesity or HF feeding." (PMID 29176715, 2017). "In vivo, several studies have shown that butyrate can alleviate high fat diet-induced obesity and improve insulin sensitivity in skeletal muscle of mice under a high fat diet." (PMID 28055958, 2017). "On the other hand, the excess adipose tissue that accompanies obesity alters the release of adipokines, including leptin and adiponectin, which are known to affect insulin sensitivity and vascular functionality, thereby, increasing the risk of MS." (PMID 28193268, 2017). "Related studies showed that chronic central and acute peripheral administration of an alpha-MSH analogue, decreased food intake and body weight and limited insulin resistance in a high-fat diet induced obesity mouse study." (PMID 29023410, 2017). "Nevertheless, genetic mouse models provided novel insight into how TNFα-induced signaling interferes with insulin signaling in obesity." (PMID 28233125, 2017). "We found that EMD mice exhibit mild obesity as a result of hyperphagia, increased adiposity, elevated leptin and insulin plasma concentration, hypertriglyceridemia, impaired glucose tolerance, and decreased hypothalamic leptin signaling." (PMID 28143489, 2017). "Many years of research have documented a positive relationship between obesity status and insulin levels in animal models and humans." (PMID 28466412, 2017). "Next, we evaluated the influence of obesity per se on insulin-stimulated phosphorylation of AKT in lung tissue in absence of allergic airway inflammation (saline-instilled mice)." (PMID 29229986, 2017). "A secondary approach to determining the role of HI in the manifestation of obesity is to inhibit insulin signaling." (PMID 28466412, 2017). "This metabolic phenotype is characterized by a favorable cardiometabolic risk profile and more specifically, reduced incidence of metabolic syndrome and obesity with a favorable lipid and insulin profile." (PMID 29253899, 2017). "Obesity induced by excess nutrient intake leads to the upregulation of mTORC1/S6K1 signaling in insulin-sensitive tissues, including β cells." (PMID 29240812, 2017). "Expression of miR-143 and miR-145 is upregulated in the liver of mouse models of obesity, and the iperexpression of miR-143 impairs insulin-stimulated AKT activation and glucose homeostasis." (PMID 28974990, 2017). "Reduced hepatic lipid content with concomitant antioxidant and anti-inflammatory responses favoring insulin sensitivity in mice with high-fat diet-induced obesity are ascribed to the repletion of liver n-3 PUFA levels by n-3 PUFA dietary supplementation." (PMID 28356106, 2017).
Obesity (continued). "These adipokines play important roles in insulin signaling and the development of a chronic low-grade inflammatory state, which is characteristic for obesity." (PMID 28686216, 2017). "Clinically the first important realization of the study is that a large number of signals can potentially influence insulin sensitivity and the current emphasis on obesity alone is perhaps overplayed and unwarranted." (PMID 28767672, 2017). "Taken together, we find that reduction Miro1 results in obesity and disturbs insulin release in mice." (PMID 29207597, 2017). "The baseline characteristics were more comparable in the matched sample and only 6 variables (i.e., age, dyslipidemia, obesity, eye disease, insulin, and sulfonylurea) differed significantly." (PMID 27861146, 2017). "This means that the intestine is an insulin-sensitive organ and intestinal insulin resistance exists in obesity." (PMID 28183816, 2017). "Seven patients with obesity underwent measurement of hepatic insulin sensitivity at baseline, 1 week after a low‐calorie liquid diet and after a further 1 week following insertion of the DJBL whilst on the same diet." (PMID 28392935, 2017). "Kappert’s group have shown that systemic administration of an SHP-1 inhibitor improves insulin sensitivity in animal models of diet-induced obesity." (PMID 27933336, 2017). "In the present study, they demonstrate that over-expression of AdiopR1 and AdipoR2 improves whole body glucose metabolism and hepatic insulin sensitivity and opposes hepatic steatosis in obesity." (PMID 28271029, 2017). "Further, an increase in saturated TGs will increase saturated diaglycerides that have been shown to decrease insulin sensitivity with a consequent promotion of obesity." (PMID 28351387, 2017). "Note that we did not use cells from the ERα−/− mice because these mice were obese and insulin-resistant from an early age33, and obesity changes ion channel activity, calcium signalling and exocytosis." (PMID 28924161, 2017). "It seems that fibrin fibres (originating mostly from grain, then from fruit and vegetables) have a protective effect on the development of coronary heart disease and obesity, among other things, by reducing the level of insulin in the blood." (PMID 28915786, 2017). "In GPx-1 overexpressing mice, increases of GPx-1 activity, ranging from 31 to 300%, were related to obesity and IR, and phosphorylation of Akt was reduced in response to insulin." (PMID 28981461, 2017). "Adipose tissue insulin sensitivity was also reduced at 8 weeks of age, which precedes the onset of obesity in the offspring of high-fat- and sugar-fed dams." (PMID 28684678, 2017). "The intravenous insulin rates remain contentious, with fixed weight-based insulin rates being advocated by national authorities, to account for changing patient demographic, including obesity and higher insulin-resistance states such as pregnancy." (PMID 28659865, 2017). "Leptin, which is produced by several tissues including white adipose tissue, stomach, mammary gland, placenta, and skeletal muscle, has actions such as insulin and regulates appetite and obesity." (PMID 28824543, 2017). "We extended these findings by demonstrating that S-nitrosation orchestrates food intake by sustaining hypothalamic insulin resistance and promoting obesity." (PMID 28835706, 2017). "Hypertension, prevalent in ≤40 years old, possibly was initial effect of lesser sensibility of insulin and inadequate eating habits; in patients aged ≥61 years old, probably was result of a longer history of obesity and worse management of insulin prescribed." (PMID 28507609, 2017). "The purpose of this study was to evaluate the association between CNVs in specific regions of LEPR, NEGR1, ARHGEF4, CPXCR1, and INS and in four intergenic regions (1p36.33b, 12q15c, 15q21.1a, and 22q11.21d) and obesity in Mexican children." (PMID 28428959, 2017).
Obesity (continued). "Numerous studies support the concept of a compromised balance between ROS generation and the antioxidant defense network in obesity and insulin-resistant states." (PMID 28439848, 2017). "These physiologic actions of insulin can partly play a role in the development of clinical obesity, hypertension (HTN), and atherosclerosis by binding to insulin receptor substrate 1, that stimulates post receptor signaling pathways." (PMID 28912752, 2017). "Collectively, these data suggest that glucose homeostasis and insulin sensitivity remain normal during obesity-related ovarian dysfunction and infertility in Mito-Ob mice." (PMID 28432106, 2017). "In conclusion, we have shown that maternal insulin is a key programming factor mediating the effects of maternal diet-induced obesity on offspring insulin sensitivity." (PMID 28291256, 2017). "This rhythm can be impaired in overweight and obesity patients wherein IR becomes a chronic response and gains an elevated threshold to insulin action." (PMID 28884000, 2017). "Circulating leptin and insulin are also detected to be elevated in other types of obesity such as induced by high-fat diet, idiopathic, and in patients with Cushing’s disease." (PMID 28101317, 2017). "Palmitoleic acid enhances insulin sensitivity by suppressing inflammation and inhibiting the destruction of insulin-secreting pancreatic β cells, and it also reduces obesity-related inflammation." (PMID 28179577, 2017). "In obesity, increased free fatty acid influx into liver impairs insulin signaling and leads to increased hepatic gluconeogenesis." (PMID 28832228, 2017). "TLR signaling is known to promote obesity-induced resistance to insulin and leptin, suggesting that upregulation of Peli3 in response to HFD is implicated in the increased serum concentrations of insulin and leptin observed in the present study." (PMID 28170448, 2017). "IFNγ-knockout in obesity improved insulin sensitivity and decreased adipocyte size, macrophage infiltration and cytokine expression." (PMID 29254175, 2017). "Arguably, leptin, for a while thought to be the panacea to beat obesity, received major attention in obesity research, whereas the role of insulin was less appreciated." (PMID 28303116, 2017). "In both obesity and metabolic syndrome, alterations occur in circulating levels of insulin and insulin-like growth factors, sex hormones, adipokines, inflammatory factors, several chemokines, lipid mediators and vascular associated factors." (PMID 28210884, 2017). "In the present study, we are the first to identify differential beta oscillatory activity and coherence in the limbic cortico-basal ganglia loop in obesity that is strongly correlated with serum insulin and leptin levels." (PMID 29138510, 2017). "INS regulates hormone stability and is also reported to contribute to obesity, confirming the potential relationship between obesity and endocrine diseases." (PMID 29258237, 2017). "These authors also showed that chronic CK2 inhibition by CX-4945-treatment for 40 days protects mice from diet-induced obesity and moderately improves insulin sensitivity by promoting UCP-1 dependent thermogenesis." (PMID 29242563, 2017). "We previously found that adaptation to obesity in terms of insulin sensitivity was characterised by a specific gut microbiota profile in insulin-resistant vs insulin-sensitive obese individuals." (PMID 28105518, 2017). "In fact, GW9662 has an anti‐obesity effect in mice, while mice heterozygous for PPARG deficiency show improved insulin sensitivity." (PMID 28275008, 2017). "Studies in rats with diet-induced obesity showed that soy isoflavones in a HFD significantly stimulated insulin secretion, decreased PPAR-γ, GLUT 2, and SREBP-1 expression, and ameliorating hyperinsulinemia observed during obesity." (PMID 28574454, 2017).
Obesity (continued). "Evidence from animal studies also suggests that HFD-induced obesity results in higher concentrations of serum leptin, insulin, and insulin-like growth factor-1 (IGF-1), and facilitates colon tumor formation." (PMID 28170448, 2017). "Studies evaluating the effects of high-saturated fat diets on cardiac function are most often confounded by diet-induced obesity and by systemic insulin resistance." (PMID 28718833, 2017). "Mice that lacked the M3 receptor displayed increased energy expenditure, were protected from obesity, and showed increased insulin sensitivity." (PMID 29281967, 2017). "(R)‐ α ‐lipoic acid (ALA), an essential cofactor in mitochondrial respiration and a potential antioxidant, possesses a wide array of metabolic benefits including anti‐obesity, glucose lowering, insulin‐sensitizing, and lipid‐lowering effects." (PMID 28603627, 2017). "For example, it has been shown that global or liver-specific overexpression of miR-26a prevented obesity-induced metabolic complications by targeting several key regulators of hepatic energy metabolism and insulin signaling in mice fed an HFD." (PMID 29207650, 2017). "Excess fuel storage in obesity culminates in stimulated growth factor signaling via the insulin/insulin-like growth factor (IGF-1) axis, and can lead to a nutrient-saturated environment with high levels of glucose and other nutrients." (PMID 29340030, 2017). "In summary we found that ATP10D reduces high-fat diet induced obesity and improves insulin sensitivity." (PMID 28542499, 2017). "Increased postprandial glucose concentration and reduced insulin sensitivity were reported in both inactive variants NBR and HBR, suggesting the onset of obesity-related symptoms." (PMID 28522975, 2017). "Adiponectin is known to increase fatty acid oxidation and insulin sensitivity and prevent obesity and inflammation." (PMID 28804438, 2017). "Activation of IKKβ associated with endoplasmic reticulum (ER) stress in hypothalamus is recently shown to link overnutrition to suppressed insulin and leptin signaling in this tissue, leading to energy imbalance, obesity, and glucose intolerance." (PMID 28797077, 2017). "As demonstrated in animal models, SCFAs, which were transported from the intestine into blood and tissue, improved insulin sensitivity and prevented metabolic diseases such as obesity and diabetes." (PMID 29051579, 2017). "At 5 weeks of diet-induced obesity, fasting plasma insulin concentration was significantly higher in HFD-CAST Tg mice compared to HFD-WT and LFD fed mice." (PMID 29089532, 2017). "After 8 weeks‐of‐age, both male and female B6 have greater adiposity in response to a HF, but only male B6 mice had a level of adiposity (>0.4) indicative of obesity and only the male B6 mice were glucose intolerant and insulin resistant." (PMID 28400497, 2017). "Formula-fed infants had a different profile of ARH than breastfed infants, suggesting that lower levels of ghrelin, leptin and insulin in breastfed infants contribute to the protective role of breastfeeding against obesity development." (PMID 27170102, 2017). "Obesity-induced inflammation appears to occur mainly in insulin-sensitive tissues (e.g., adipose tissue, liver and muscle) in obese humans, especially those with symptomatic metabolic disorders." (PMID 29040966, 2017). "Using high glucose and fatty acids-treated HepG2 cells and high fat diet (HFD)-induced obesity mice, we detected its effect on insulin function and lipid metabolism based on autophagy." (PMID 28452943, 2017). "The increasing on serum uric acid level is related to other conditions than gout, like cardiovascular diseases, obesity, hypertension, and resistance to insulin." (PMID 29375639, 2017). "Some evidence suggests that resistin modulates glucose tolerance and insulin action, thereby playing a role in the pathogenesis of obesity and insulin resistance in humans." (PMID 29386698, 2017).
Obesity (continued). "The ability of chronically elevated palmitate levels to simultaneously increase basal secretion of glucagon and insulin positions elevated levels of fatty acids as potential triggering factors for the development of obesity and impaired glucose control." (PMID 28680093, 2017). "It is well known that one of the major hypothalamic molecular disorders attributed to obesity is the insulin inability to propagate its intracellular signal, which results in lower Akt phosphorylation." (PMID 29062272, 2017). "HDAC inhibition also generates non-traditional effects such as reducing adipose tissue expansion, resistance to obesity, and improvement in insulin sensitivity." (PMID 28261159, 2017). "PTPs have control over both leptin and insulin signaling,therefore inhibition of PTPase activity seems to be an appealingstrategy for obesity and diabetes." (PMID 29379255, 2017). "It is generally considered that obesity measures and insulin levels can influence each other based on pathophysiological and metabolic mechanisms." (PMID 28230104, 2017). "In Iranian obese subjects, it seems the Pro/Pro polymorphism of the PPAR-γ2 gene induce favourable effects on obesity management and insulin sensitivity." (PMID 28761824, 2017). "In this study, we found significant differences in the copy numbers among children with obesity compared to those in normal weight children for LEPR, NEGR1 ARHGEF4, CPXCR1, and INS and four intergenic regions previously associated with obese children." (PMID 28428959, 2017). "One explanation for a potentially adverse influence of adiposity on bone involves obesity-related metabolic health outcomes, specifically insulin resistance." (PMID 28286536, 2017). "We focused on adipose tissue insulin signaling, inflammation as well as MAP kinase stress signaling and ATM lipid content, all of which were implicated in the pathogenesis of obesity-related whole-body and liver metabolic dysfunction." (PMID 28360082, 2017). "Despite the severe obesity resulting from mitoNEET overexpression in ob/ob mice, the insulin sensitivity is preserved." (PMID 29311966, 2017). "In obesity the pancreatic islet beta-cells respond to increased nutrient status and insulin resistance with increased insulin secretion." (PMID 28448538, 2017). "We suggest that Creb/Crtc2 negatively regulates the Sirt1/Pparα/Fgf21 axis via the induction of miR-34a under diet-induced obesity and insulin-resistant conditions." (PMID 29192248, 2017). "Induction of heme oxygenase-1 (HO-1) has been demonstrated to decrease body weight and improve insulin sensitivity in several models of obesity in rodents." (PMID 28287466, 2017). "Such well-known associations emphasize the importance of these two adipokines connecting adipose tissue biology, obesity, and insulin sensitivity." (PMID 28626772, 2017). "Studies in cultured hepatocytes and mouse models of diet-induced obesity suggest that palmitoleic acid has anti-inflammatory and insulin-sensitizing effects." (PMID 28327516, 2017). "Under insulin-resistant conditions such as obesity, pancreatic β-cells proliferate to prevent blood glucose elevations." (PMID 29208957, 2017). "An inflammatory state in the hypothalamus disrupts its ability to sense metabolic abnormalities, affecting energy balance and glucose metabolism, leading to obesity and insulin resistance." (PMID 28544365, 2017). "In contrast, serum insulin levels were markedly elevated in HFD-induced obesity in sham or TAMR1 obese mice." (PMID 28145500, 2017). "At 16 weeks of diet-induced obesity, plasma insulin concentration was significantly higher in both HFD- WT and Tg mice (Figure SIII in the online-only Data Supplement)." (PMID 29089532, 2017). "MiRNAs play regulatory roles in obesity by regulating adipocyte differentiation, insulin activity, and fat metabolism." (PMID 28445161, 2017).